TNF (tumor necrosis factor)
Diseases named in the same sentence as TNF in open-access papers (continued):
Sharing a sentence is not in itself a finding about the gene and the disease.
colitis (continued). "Additionally, anti‐CD40‐induced colitis mice showed significantly higher levels of mRNA expression of proinflammatory cytokines IL‐1β, IFNγ, and TNFα in colonic mucosa when compared to controls." (PMID 40410944, 2025). "Based on human UC biopsy sample examination and an animal model of colitis (induced by dextran sulfate sodium - DSS in CHGA gene knockout mice), a positive correlation between CgA and M1 macrophage-associated pro-inflammatory cytokines such as IL-1β, IL-6, and TNF have been observed." (PMID 40370467, 2025). "In vivo studies demonstrated that AOE reduced DSS-induced colitis in mice by increasing the colon length, enhancing antioxidant enzyme activity, inhibiting inflammatory cell infiltration, suppressing the formation of TNF-α and IL-6, and reducing malondialdehyde (MDA) levels." (PMID 39857378, 2025). "In addition, during the acute phase of colitis caused by DSS, serum from C57BL/6J mice exhibits a cytokine expression pattern characterized by TNF-α, IFN-γ, and IL-6 from M1 macrophages/Th1 cells and IL-17 from Th17 cells similar to the expression pattern found in colon." (PMID 39176394, 2024). "In addition, electroacupuncture stimulation of “Zusanli” (ST36) activated Ach release from the VN in the colon to significantly reduce plasma TNF-α, IL-1β, and IL-6 levels, decrease the disease activity index, and increase daily food intake in a rat model of colitis." (PMID 39355776, 2024). "Upon stimulation with CHX and TNF-α, a detrimental proinflammatory cytokine underlying mucosal damage in IBD, cell viability was comparable between YOD1-deficient and -sufficient Mode-K cells, decreasing the possibility that YOD1 affects colitis by regulating the apoptosis of IECs." (PMID 39333628, 2024). "Relevant scholars have suggested that the therapeutic effect of mannose on DSS-induced colitis may be related to the regulation of macrophage polarization in the colon that may involve the release of TNF-α and pathological endoplasmic reticulum stress of intestinal epithelial cells." (PMID 38529272, 2024). "Furthermore, TNFα will promote angiogenesis and intraepithelial cell damage, induce Paneth cell death, and activate both macrophages and effector T cells in animals with colitis." (PMID 38992956, 2024). "To verify our hypothesis that IA-0130 suppresses the excessive expression of pro-inflammatory cytokines, we analyzed the mRNA and protein expression of pro-inflammatory cytokines, TNF-α, IL-1β, IL-6, and IL-17A, which are important in colitis development and maintenance." (PMID 38916850, 2024). "We further examined whether macrophage iron export could affect TNF‐α production in colitis." (PMID 38235606, 2024). "Likewise, this compound suppressed DC-induced inflammatory cytokine production by attenuating the transcription factor PU.1 and promoting Foxp3+ Treg differentiation, effectively alleviating symptoms of DSS-induced colitis and decreasing TNF-α expression in mice." (PMID 39494333, 2024). "Our findings show that Cyn significantly alleviates TNBS-induced colitis symptoms in mice, as evidenced by reduced body weight loss, colon shortening, DAI score, colon histopathology score, and lower levels of inflammatory factors (IL-1β, TNF-α, and IL-6) compared to the model group." (PMID 39902073, 2024). "Animal experiments using a DSS-induced colitis-mouse model revealed that oral administration of Trp, abundantly contained in ED, attenuated inflammation, and its effective mechanism may involve a decrease in TNF-α and an increase in IL-10." (PMID 38542428, 2024). "In addition, RT-qPCR and the ELISA assay demonstrated that the pro-inflammatory cytokines of TNF-α, IL-1β, and IL-6 increased in number in the colitis tissues and sera, whereas UTI could reverse this pro-inflammatory phenotype." (PMID 38397811, 2024).
colitis (continued). "Similarly, Billy and colleagues reported that long-term Blastocystis ST3 colonization in rats attenuated the gut inflammation and colitis and enhanced their recovery by affecting the gut ecosystem, reducing inflammatory cytokines (TNF-α and IL-1β), and stimulating IL-17 (IL17re/IL17C) transcripts." (PMID 39338600, 2024). "Moreover, another study also proposed that ginsenosides Rd was able to effectively alleviate DSS colitis in mice through inhibiting proinflammatory cytokines expression (TNF-α, IFN-γ, IL-6, IL-12/23p40, and IL-17A) and inhibiting NF-κB and P38MAPK signaling pathways." (PMID 38698858, 2024). "In a mouse model of DSS-induced colitis, it was shown that S. cerevisiae supplementation increased the expression of anti-inflammatory cytokines (IL-4 and IL-10), while reducing the disease activity index and the expression of pro-inflammatory cytokines (TNF-α, IL-6 and IL-17F)." (PMID 38540191, 2024). "Interestingly, although ACRE appears to act locally rather than systemically, other studies have shown that inflammation-modulating interventions, like dried bilberries in a colitis model, can reduce both local and systemic inflammatory markers, such as TNF and interferon-γ." (PMID 39597764, 2024). "Additionally, POL has been shown to effectively attenuate DSS-induced colitis by inhibiting oxidative stress responses, such as nitric oxide and superoxide dismutase, as well as reducing the levels of pro-inflammatory cytokines like TNF-α, IL-1β, and IL-6." (PMID 37653406, 2023). "Nevertheless, the levels of TNF-α in these tissues were significantly reduced to similar levels to those of the normal control groups when the probiotic L. paracasei strain MSMC39-1 was fed to the colitis rats (*** p < 0.001 when compared to the colitis control group)." (PMID 36986118, 2023). "The impaired clinical recovery in both acute and repair phases of colitis in mice treated with MLT could be linked to the increase in circulating leukocyte and TNF production in the colon, despite reduced IL-17 cytokine, which is fundamental for gut immunity in the control of bacteria burden." (PMID 36838425, 2023). "Besides, FMT rescued the elevated inflammatory factors TNF-α, IL-6, and IL-1β in serum and colonic tissue of mice colitis model, indicating that both of CA- and EA-altered microbiota can effectively transfer the colitis protection." (PMID 37813835, 2023). "Neutrophil-depleted mice developed more severe colitis than controls, characterized by significant weight loss, aggravated histological lesions, impaired mucosal barrier function, and expression of proinflammatory cytokines (e.g., IL-1β, IL-17A, IFN-γ and TNF-α) in the colon tissues." (PMID 36729914, 2023). "However, it is still unclear if Blautia is effective for treating colitis because it helps to enhance the creation of SCFAs, while is concentrated in UC patients’ gut and positively correlates with IL-1β, IL-6, and TNF-α." (PMID 37297494, 2023). "A previous study demonstrated that butyrate inhibits the NF-kappa B signaling pathway in LPS-stimulated RAW264.7 cells and ameliorates colitis in Il10−/− mice, indicating the possibility that butyrate derived from AX might directly suppress TNFα production from Th1 cells as well as macrophages." (PMID 37049841, 2023). "They showed that it could reduce MDA, NO, MPO, hydroxyproline, TNF-α, IL-1β, IL-6, iNOs mRNA, COX-2 mRNA, IFN-γ mRNA, Bcl-2-associated X protein (Bax), Caspase-1, NF-kB and IκBα and increase IL-10, SOD and GSH in an in vivo model of TNBS-induced colitis." (PMID 36677021, 2023). "It is unknown why TNF inhibition would trigger mainly CD or unclassified colitis." (PMID 37629636, 2023). "Moreover, aesculin and aesculetin, another two natural compounds of FC, were proved to relieve the symptoms of DSS-induced colitis, restrain the secretion of TNF-α, IL-1β through inhibiting the activation of NF-κB and MAPKs pathway in colonic tissues and macrophages." (PMID 37161415, 2023).
colitis (continued). "Additionally, in an acute colitis model, administration of 200 mg/kg of polysaccharide from D. officinale alleviated liver damage by increasing antioxidant enzyme activity and downregulating the tumor necrosis factor-α (TNF-α) signaling pathway." (PMID 38137890, 2023). "Compared with the CT group, a colitis model was successfully constructed in the DSS group, as evidenced by higher weight loss, an increased DAI, shorter colon length, more serious colonic tissue damage, and higher levels of pro-inflammatory cytokines (IL-6, IL-1β, TNF-α, and IL-1α)." (PMID 37505716, 2023). "Our results showed that DSS-induced acute colitis led to impaired autophagy flux in IECs, and that administration of oat beta-glucan could promote autophagy flux in IECs, downregulate the expressions of IL-1β, IL-6 and TNF-α and reduce intestinal inflammation." (PMID 37441529, 2023). "Similarly, long-term colonization with Blastocystis ST3 could promote faster recovery from colitis and decrease the expression of TNFα and IL-1β in dinitrobenzene sulfonic acid (DNBS)-induced colitis mice." (PMID 37185924, 2023). "It is known that TLR8 activation can enhance TNF and IL-1β production, both associated with mucosal inflammation in UC, whereas TLR7 agonists could induce a type I IFN response and prevent experimental colitis in mice." (PMID 37446274, 2023). "Therefore, it is possible that OJS could ameliorate colitis and/or colitis symptoms, such as visceral hypersensitivity, by inhibiting TNFα release from macrophages." (PMID 37049400, 2023). "TNF-α–siRNA and gallic acid – mediated graphene quantum dots (GAGQDs) encapsulated in bovine serum albumin nanoparticles were demonstrated to effectively treat colitis, maintain bacterial gut microbiota homeostasis, and modulate mood and cognitive dysfunctions in mice." (PMID 38024319, 2023). "Interestingly, the CRAC channel inhibitor BTP2 or CM4620 was shown to significantly reduce the production of inflammatory cytokines (such as IFNγ, TNF, IL-17A, IL-13, and IL-4) from human intestinal T cells, B cells, ILCs and myeloid cells, and improve colon inflammation in a mouse model of IBD." (PMID 36459135, 2023). "In a dextran sodium sulfate (DSS)-induced murine colitis model, mice with oral stigmasterol administration had a delayed onset of colitis, a reduced pathohistological score in the colon; and a downregulated expression of inflammatory factors, including IL-6, IL-1β, and TNF-α." (PMID 37685017, 2023). "After induction of colitis by DSS, there was weight loss, diarrhea, fecal bleeding, increased mortality, ulcers, loss of colon, and inflammation configured by cellular infiltration, the elevation of pro-inflammatory cytokines (IL-1β, IL-18, TNF-α, and IL-6) and NO." (PMID 36677021, 2023). "We cannot exclude that the present results could be partially related to their higher content of rosmarinic acid, which displayed anti-inflammatory effects in experimental models of colon inflammation, including the capability to reduce the production of TNFα and COX-2." (PMID 37570939, 2023). "Finally, the protective effects of the extracts, measured as inhibition of COX-2 and TNFα gene expression, were assayed in an ex vivo experimental model of colon inflammation, constituted by isolated mouse colon specimens challenged with lipopolysaccharide (LPS)." (PMID 37570939, 2023). "Thus, PNE significantly reduced serum TNF‐α compared to the colitis control." (PMID 37249276, 2023). "Interestingly, also memantine acting by blocking N-methyl-D-aspartate (NMDA) receptors significantly attenuates macroscopic and microscopic signs of colitis in a mouse model decreasing the plasma levels of interleukin-1β, interleukin-6, and colon level of tumor necrosis factor-α and myeloperoxidase." (PMID 34797427, 2022). "The worse survival in anti-TNF-treated patients was also not linked to colitis." (PMID 35538491, 2022). "Finally, we found that TNF produced by IECs controls IL-22BP production during colitis." (PMID 35383266, 2022).
colitis (continued). "The decrease of NF-κB and TNF-α could be caused by cell apoptosis, as necrotic tissue could be seen under the microscope, meaning they were not damage factors in the colitis." (PMID 35844499, 2022). "In a colitis-associated colon cancer mouse model, L. bulgaricus decreased intestinal inflammation and reduced tumour levels of IL-1β, IL-6, IL-17, IL-23 and TNF-α; L. acidophilus, L. rhamnosus and B. bifidum also reduced TNF-α and increased IL-10 in the colon of this mouse type." (PMID 35408849, 2022). "However, on the other hand, IL-18 is thought to promote the ability of colitis by inducing inflammatory mediators such as TNFα and chemokines, inhibition of IL-18 has also been shown to trigger protection in experimental colitis, supporting the role of IL-18 in exacerbating colitis." (PMID 35677444, 2022). "Similarly, members of the genus Parabacteroides including Parabacteroides distasonis were previously found to be decreased in autoimmune disease and to reduce the severity of intestinal inflammation in colitis in mice through decreased production of proinflammatory cytokine TNF-α." (PMID 36482486, 2022). "In a rat model of DSS-induced colitis, the oral administration of Lf induced a significant increase in anti-inflammatory cytokines (IL-4 and IL-10) and a significant reduction in pro-inflammatory cytokines (TNF- α, IL-1β and IL-6), with a consistent improvement in disease severity." (PMID 35407131, 2022). "In addition, prophylactic administration of EGCG could reduce the levels of plasma IL-1β, IL-6, IL-8, and TNF-α in mice with colitis induced by DSS, indicating that EGCG can alleviate the symptoms of colitis, colonic injury, and inflammation." (PMID 35276917, 2022). "Moreover, a previous study showed that oral administration of the AhR agonist β-naphthoflavone decreased DSS-induced colitis severity and the production of pro-inflammatory cytokines, such as tumor necrosis factor (TNF)-α, IL-6, and IL-1β, which was consistent with our results." (PMID 36613665, 2022). "Importantly we see evidence of upregulation of TNF-α, IL-1β, and IL-6 in various brain regions of colitis models, which may be sourced from or interact with neurons, microglia, and other cells." (PMID 34983592, 2022). "The decrease in NF-κB mRNA and TNF-α might be caused by cell apoptosis, and necrotic tissue was found under the microscope, so they were not damage factors in the colitis." (PMID 35844499, 2022). "EVs decreased NF-κB levels and mRNA levels of TNFα, IL-1α, IL-1β and IL-2, and increased mRNA levels of TGFβ and IL-10 in LPS-induced inflammation in human intestinal epithelial cells (HT-29) and reduce inflammation symptoms of dextran sulfate sodium-induced colitis in mice." (PMID 35432276, 2022). "Finally, genetic ablation of TNF in distinct cellular sources in this colitis model revealed that soluble TNF produced by IECs controls IL-22BP expression in the colon, while transmembrane T cell-derived TNF regulated inflammation and TNF production by IECs and, thereby, Il-22 bioactivity." (PMID 35383266, 2022). "Administration of 25.2 g/kg BW of FBPE decreased the IFN-γ, TNF-α and IL-4 levels, while enhancing the IL-10 level, and significantly inhibited the abnormally decreased IgG (Model: 13.25 mg/mL, HD: 14.06 mg/mL), showing a reversal effect on the Th1/Th2 levels in colitis." (PMID 35564016, 2022). "The oral GSK3-α/β and CDK9 inhibitor, ABC1183, led to a dramatic improvement in dextran sulfate sodium- and 2,4,6-trinitrobenzene sulfonic acid- induced colitis that was associated with suppression of TNF-α and IL-6, and no observed organ or hematological toxicity." (PMID 35660024, 2022). "The treatment was tested during and after colitis induction and the results showed that early treatment (days 0 and 3) attenuated acute colitis, with significantly lower concentrations of inflammatory cytokines (TNF-α and IL-6) in the colonic mucosa, compared to untreated animals." (PMID 35939430, 2022).
colitis (continued). "While CD40/TNFRS5 is one of the TNF-α receptors involved in colitis associated to IL-1β production, no significant variation was found in TNFα, IL-6, and adiponectin expression levels between HL-ARA and HL + ARA groups compared with the mice fed the Std-ARA diet." (PMID 36558497, 2022). "Furthermore, IP administration reduced disease severity in the DSS colitis model, and this was accompanied by a decrease in the expression of pro-inflammatory cytokines IL-12, TNF, IFNγ, and IL-1β, and an increase in the expression of the anti-inflammatory cytokine IL-10." (PMID 35052669, 2022). "Further analysis of human and murine TNF expression in sera of Rag1−/− recipient mice of hTNF-KI T cells revealed significantly higher soluble murine TNF production as compared with soluble hTNF, suggesting that TNF by T cells is mostly produced in membrane-bound form during colitis." (PMID 35383266, 2022). "Next, we addressed whether anti-mouse TNF blockade during colitis also affected IL-22BP expression." (PMID 35383266, 2022). "Comparing the transcriptomes of mice with DSS-induced colitis (without SpNS) and control mice indicated an expected induction of genes encoding pro-inflammatory cytokines, such as TNF-α, and genes involved in wound healing and remodeling, such as Matrix Metalloproteinase (MMP)-7." (PMID 35715845, 2022). "Indeed, this may be consistent with studies that observed normalisation of synaptic transmission following either anti-TNF-α or minocycline treatment in animals with colitis." (PMID 34983592, 2022). "In mice colitis models, we demonstrated that orally administrated of TDNPs 2 could ameliorate mice colitis and accelerate colitis resolution via regulating the expression of the pro-inflammatory cytokines, including TNF-α, IL-6, and IL-1β, and antioxidant gene, HO-1." (PMID 35488343, 2022). "Similar alleviation of colitis was observed in mice with orally administered broccoli-derived nanoparticles that appear to target mesenteric lymph nodes and intestinal DCs, in which a reduction in TNF-α, IFN-γ and IL-17A, as well as overexpression of IL-10 was observed." (PMID 35886902, 2022). "In summary, our work revealed that the knockout of GPR174 could reduce intestinal inflammation and repair the epithelium barrier by suppressing DCs maturation and naïve T cell differentiation to alleviate DSS-induced colitis, which was probably through inhibiting the TNF-α (NF-κB) pathway." (PMID 35669778, 2022). "To determine whether Pacer could be involved in the response of MSC to an inflammatory environment during colitis, we first assessed the levels of Pacer and other autophagy markers by Western blot in the presence of TNFα, since this cytokine plays an important role in the pathogenesis of colitis." (PMID 35563809, 2022). "In addition to being effective in treating colitis, evidence in mice points towards TNF blockade enhancing the anti-tumour effects of ICI by increasing infiltration of tumour-specific T cells in the tumour and decreasing activation-induced cell death in CD8 + T cells." (PMID 34338882, 2021). "To explore the potential effects of extracellular ATP on colitis, we screened all the purinergic receptors in both human and mouse transcriptional datasets and found that P2RX1 was significantly upregulated in inflamed colon and associated with anti-TNF-α therapy efficiency." (PMID 34354708, 2021). "However, for comparison, in the treatment of colitis, 0.005 to 0.23 mg of the substance was administered via one subcutaneous injection every 2 days for 8 days, with results comparable to the administration of 0.03 mg of an anti-TNF-α antibody." (PMID 33498456, 2021). "Similarly, in the present study, we also found that the levels of serum IL-1β, IL-6, and TNF-α were increased in DSS-induced colitis, while LSE supplementation could decrease these inflammatory cytokines." (PMID 35059326, 2021).